CFAP97 (cilia and flagella associated protein 97)
Synonyms: KIAA1430; DKFZp434F1728; hmw
Tractability: PROTAC: ubiquitination databases record sites on it.
Gene: Protein-coding gene on chromosome 4 (185,159,665 to 185,210,815, reverse strand). Ensembl gene ENSG00000164323.
Subcellular location (Human Protein Atlas): Nucleoli fibrillar center; Cytosol; Primary cilium
Genetic constraint (gnomAD): Loss-of-function variants: 36 observed, 43.4 expected, observed/expected ratio (o/e) 0.83, 90% interval 0.63 to 1.1. The upper end of that interval is the gene's LOEUF score, 1.1, which puts it in group 4 of 6, group 1 being the genes least tolerant of losing a copy. Missense variants: 642 observed, 625.85 expected, observed/expected ratio (o/e) 1.03, 90% interval 0.96 to 1.1. Synonymous variants: 226 observed, 228.83 expected, observed/expected ratio (o/e) 0.99, 90% interval 0.88 to 1.1.
Homologues: Orthologues: chimpanzee CFAP97 (97% identical), macaque CFAP97 (95% identical), rabbit CFAP97 (78% identical), dog CFAP97 (78% identical), pig CFAP97 (76% identical), guinea pig CFAP97 (75% identical), rat Cfap97 (73% identical), mouse Cfap97 (70% identical), tropical clawed frog cfap97 (40% identical), zebrafish cfap97 (27% identical).
Diseases named in the same sentence as CFAP97 in open-access papers:
CFAP97 is named in the same sentence as 2 diseases in open-access papers, as found by Europe PMC text mining. Sharing a sentence is not in itself a finding about the gene and the disease.
CFAP97 shares sentences with these, for which no sentence is quoted: diabetes (1 paper); Obesity (1).